ANKDD1A (ankyrin repeat and death domain containing 1A)
Synonyms: FLJ25870
Tractability: PROTAC: ubiquitination databases record sites on it.
Gene: Protein-coding gene on chromosome 15 (64,911,861 to 64,958,700, forward strand). Ensembl gene ENSG00000166839.
Subcellular location (Human Protein Atlas): Nucleoplasm
Gene Ontology:
Molecular function: protein binding
Biological process: signal transduction
Genetic constraint (gnomAD): Loss-of-function variants: 50 observed, 55.67 expected, observed/expected ratio (o/e) 0.9, 90% interval 0.71 to 1.14. The upper end of that interval is the gene's LOEUF score, 1.14, which puts it in group 4 of 6, group 1 being the genes least tolerant of losing a copy. Missense variants: 540 observed, 577.83 expected, observed/expected ratio (o/e) 0.93, 90% interval 0.87 to 1. Synonymous variants: 229 observed, 233.43 expected, observed/expected ratio (o/e) 0.98, 90% interval 0.88 to 1.1.
Homologues: Orthologues: chimpanzee ANKDD1A (99% identical), macaque ANKDD1A (83% identical), rabbit ANKDD1A (78% identical), rat Ankdd1a (77% identical), mouse Ankdd1a (76% identical), dog ANKDD1A (66% identical), pig ANKDD1A (62% identical), tropical clawed frog ankdd1a (57% identical), zebrafish ankdd1a (53% identical). Paralogues in human: ANKDD1B (36% identical).
Diseases named in the same sentence as ANKDD1A in open-access papers:
ANKDD1A is named in the same sentence as 6 diseases in open-access papers, as found by Europe PMC text mining. Sharing a sentence is not in itself a finding about the gene and the disease. The quoted sentences say what the papers report.
glioblastoma (7 papers, 2019 to 2025). The most malignant astrocytic tumor (WHO grade IV). "ProCyon’s generation that ANKDD1A inhibits cell proliferation is supported by evidence that its restored expression suppresses glioblastoma growth and invasion." (PMID 41279541, 2025). "ANKDD1A has been described as a functional tumor suppressor with germline variants predicting poor patient outcomes in low grade glioma, and is frequently methylated in glioblastoma multiforme and in clinically non-functioning pituitary adenomas." (PMID 33245713, 2020). "In addition, hypermethylation of ANKDD1A in glioblastoma has been reported; this gene interacts with FIH1 and decreases HIF1-α stability to inhibit cell autophagy in a hypoxic microenvironment, but its function in pituitary adenoma or the significance of promoter methylation is still unclear." (PMID 31796052, 2019). "In glioblastoma cells, the TSG ANKDD1A (ankyrin repeat and death domain containing 1A) was also frequently silenced by hypermethylation." (PMID 31861179, 2019). "In addition, ANKDD1A decreases the half-life of HIF1α by upregulating FIH1, decreases glucose uptake and lactate production, inhibits glioblastoma multiforme (GBM) autophagy, and induces apoptosis in GBM cells under hypoxia." (PMID 30082910, 2019).
glioma (4 papers, 2011 to 2023). A benign or malignant brain and spinal cord tumor that arises from glial cells (astrocytes, oligodendrocytes, ependymal cells). "By MethPrimer analysis, we found that the ANKDD1A promoter contained a CpG island (region −400 bp to +400 bp from transcription start site), indicating that hypermethylation may cause the decreased expression of ANKDD1A in glioma." (PMID 30082910, 2019). "In gliomas, the low expression of ankyrin repeat and death domain-containing 1 A (ANKDD1A) was due to the aberrant methylation of a promoter CpG." (PMID 37394582, 2023). "Kaplan–Meier analysis also demonstrated that there were longer survival times for glioma patients with relatively high ANKDD1A than for those with lower ANKDD1A expression." (PMID 30082910, 2019). "In this study, we first verified that ANKDD1A is frequently silenced or has lower expression level in glioma mainly due to its abnormal promoter CpG methylated modification." (PMID 30082910, 2019). "Methylation-specific PCR showed that ANKDD1A was hypermethylated in most glioma tissues (12/14) but only partially methylated in normal brain tissues (1/8)." (PMID 30082910, 2019). "Our data also indicated that ANKDD1A reduced tumor cell glucose uptake and lactic acid production under hypoxia, inhibited cell autophagy, induced apoptosis, and increased the glioma patient survival." (PMID 30082910, 2019). "Overall, these results demonstrated that CpG hypermethylation at the ANKDD1A promoter region directly contributed to the decreased expression of ANKDD1A in glioma." (PMID 30082910, 2019). "In previous studies, we found a new hypermethylated gene in glioma, ANKDD1A, which is an unnoticed gene with unknown function." (PMID 30082910, 2019). "Thus, we further designed bisulfite sequencing PCR (BSP) and methylation-specific PCR (MSP) to validate the hypermethylation of ANKDD1A in glioma." (PMID 30082910, 2019). "Moreover, to examine the clinical effect of ANKDD1A-inhibiting glioma proliferation in more detail, we isolated and cultured primary cells derived from glioma patients (hereafter referred to as PG)." (PMID 30082910, 2019). "Given that the hypermethylation of the ANKDD1A promoter occurred predominantly in low grades of glioma, it is possible that the ANKDD1A may also function to be a suppressor in human glioma and inhibit the development of glioma at the early stage." (PMID 21962230, 2011). "The TCGA database analysis (G4502A) indicated that ANKDD1A had decreased the expression in glioma compared with normal brain tissues, and this expression pattern was further confirmed by real-time PCR in glioma tissues (n = 27) and normal brain tissues (n = 10)." (PMID 30082910, 2019). "Similarly, using high-resolution bisulfite genomic sequencing to analyze the methylation state in 33 CpG sites within the CpG island of the ANKDD1A gene, we found that there were more (20/33) methylated CpG sites in the ANKDD1A gene promoter in glioma compared to normal brain tissues." (PMID 30082910, 2019). "Thus, high ANKDD1A levels act as a favorite prognosis factor for glioma patients." (PMID 30082910, 2019). "Moreover, ANKDD1A is highly frequently methylated in glioma, and the tumor-specific methylation of ANKDD1A indicated that it could be used as a potential epigenetic biomarker and possible therapeutic target." (PMID 30082910, 2019). "More importantly, the methylation levels of the ANKDD1A and PHOX2B promoters tended to be negatively correlated with age and the differentiation grades of human glioma." (PMID 21962230, 2011). "Eight promoter-hypermethylated genes (ANKDD1A, GAD1, HIST1H3E, PCDHA8, PCDHA13, PHOX2B, SIX3, and SST) were confirmed in primary glioma and cell lines." (PMID 21962230, 2011). "The methylation levels of seven gene promoters (ANKDD1A, GAD1, SIX3, SST, PHOX2B, PCDHA8, and HIST1H3E) in glioma patients and cell lines were significantly higher than those in non-tumor controls (p < 0.01)." (PMID 21962230, 2011).
glioma (continued). "In addition, ANKDD1A also decreased the half-life of HIF1α by upregulating FIH1, decreased glucose uptake and lactate production, inhibited glioma cell autophagy, and induced apoptosis in GBM cells under hypoxia." (PMID 30082910, 2019). "In addition, we found that the percentages of promoter methylation in the ANKDD1A and PHOX2B, but not the GAD1, HIST1H3E, PCDHA8, PCDHA13, SIX3 and SST, were associated negatively with the differentiation degrees of human gliomas." (PMID 21962230, 2011).
pituitary adenomas (3 papers, 2019 to 2025). "Additional genes—PHYHD1, LTBR, MYBPHL, C22orf42, PRR5, ANKDD1A, RAB13, CAMKV, KIFC3, WNT4, and STAT6—were implicated in the invasive behavior of non-functioning pituitary adenomas (NFPAs)." (PMID 39859246, 2025).
astrocytoma (1 paper, 2019). "In our research, we first found that ANKDD1A plays an important role in regulating the stability of HIF1α in astrocytoma cells under hypoxic conditions." (PMID 30082910, 2019). "Consistently, the overexpression of ANKDD1A increased cell apoptosis under hypoxia in astrocytoma." (PMID 30082910, 2019). "When both pcDNA3.1-ANKDD1A and pGL3-CA9 plasmids were co-transfected in HEK293T and astrocytoma cells, we found that the ectopic expression of ANKDD1A dramatically reduced the FLuc activity under hypoxic stress but only slightly decreased it under normoxia." (PMID 30082910, 2019).
tumor (7 papers, 2011 to 2024). "Among these survival-related genes, FGL1 and ANKDD1A were intriguingly closely associated with the tumor microenvironment and immune infiltration." (PMID 33832428, 2021). "ANKDD1A (Ankyrin Repeat And Death Domain Containing 1 A) is a functional tumor suppressor gene and involved in signal transduction." (PMID 35953519, 2024). "Here, we reported a new hypermethylated gene, ANKDD1A (ankyrin repeat and death domain-containing 1A), which acts as a tumor suppressor in GBM, especially under hypoxia." (PMID 30082910, 2019). "Of note, the re-expression of ANKDD1A significantly decreased tumor cell invasion under normoxia and hypoxia conditions." (PMID 30082910, 2019). "Most tumor samples had low ANKDD1A expression levels (17/27), and others had relatively medium or high expression levels (10/27)." (PMID 30082910, 2019). "To evaluate if ANKDD1A possessed in vivo anti-tumor capabilities, we established a subcutaneous transplantation tumor model in nude BALB/c mice using U251 cells." (PMID 30082910, 2019). "Our studies indicated that ANKDD1A expression inhibited tumor growth in vivo and extended mouse overall survival." (PMID 30082910, 2019). "The tumor-specific methylation of ANKDD1A indicates that it could be used as a potential epigenetic biomarker as well as a possible therapeutic target." (PMID 30082910, 2019). "The DNA methylation and expression levels of PHYHD1, LTBR, MYBPHL, C22orf42, PRR5, ANKDD1A, RAB13, CAMKV, KIFC3, WNT4 and STAT6 are associated with tumor invasion, and these genes may become the potential genes for targeted therapy." (PMID 31796052, 2019). "Therefore, ANKDD1A could act as a tumor suppressor gene in GBM, especially under hypoxia conditions." (PMID 30082910, 2019). "We suspect that the upregulation of FIH1 and PHD2 will act as a tumor suppressor in GBM under normoxia; this may be the mechanism for ANKDD1A biological effects in normoxia." (PMID 30082910, 2019).
cancer (1 paper, 2020). A tumor composed of atypical neoplastic, often pleomorphic cells that invade other tissues. "Three of these (lnc-SPG21-45, lnc-NSUN6-1 and lnc-KLHL28-1) are antisense to ANKDD1A, CACNB2 and C14orf28 genes, respectively, which are associated with other cancers and diseases, possibly by regulating their expression." (PMID 33245713, 2020).